TNF (tumor necrosis factor)
Diseases named in the same sentence as TNF in open-access papers (continued):
Sharing a sentence is not in itself a finding about the gene and the disease.
depression (continued). "Depression has an inflammatory component with elevated levels of proinflammatory cytokines, such as tumor necrosis factor-alpha (TNF-α), interleukin (IL)-6, IL-1, and C-reactive protein." (PMID 34948222, 2021). "Studies suggest that depression is associated with elevated levels of both pro-inflammatory and anti-inflammatory cytokines, e.g., IL-1β, IL-6, IFN-γ, TNF-α, and C-reactive protein (CRP)." (PMID 33920992, 2021). "In subjects with depression, the level of TNF-α and IL-6 had a negative correlation with the number of EPC." (PMID 34421539, 2021). "Previous studies have shown that TNF-α in plasma and cerebrospinal fluid was correlated with depression symptoms and anxiety." (PMID 34439331, 2021). "A number of studies reported people with depression to have higher levels of circulating proinflammatory cytokines, interleukin-1β (IL1β) and TNFα and interleukin-6 (IL-6)." (PMID 33919670, 2021). "TNF-α is one of the key proinflammatory cytokines, which is relevant to pathogenesis of depression through activating hypothalamopituitary-adrenocortical (HPA) axis." (PMID 33628324, 2021). "In the present study, many anti-depressant targets of EMO against depression were associated with the inflammatory response such as IL6, TNF, IL10, CRP, IL1B, CTLA4, ALB and IL2." (PMID 34051074, 2021). "Along this line, it is of interest that RA patients that received TNF-α inhibitors as a standard-of-care treatment for RA also exhibited an improvement regarding their depression." (PMID 33530359, 2021). "Subsequent research showed that administration of low-dose endotoxin (e.g., lipopolysaccharide (LPS)) increases systemic markers of inflammation including tumor necrosis factor alpha (TNFα) and interleukin 6 (IL-6) and symptoms of depression." (PMID 33967944, 2021). "In previous studies of adult and pediatric depression, plasma levels of TNF-α levels showed mixed results." (PMID 34576215, 2021). "Meta-analyses reported strong evidence of significantly increased levels of c-reactive protein (CRP), IL-1, IL-6, TNF-α and soluble IL-2 receptor in the serum of major depressive disorder (MDD) patients." (PMID 34440101, 2021). "Adult patients with major depression show increased levels of inflammatory cytokines including interleukin (IL)-6 and tumor necrosis factor (TNF) in peripheral blood and cerebrospinal fluid." (PMID 34927102, 2021). "The pro-inflammatory cytokines, IL-6 and TNF-α, are increased not only in infectious diseases, but also in major depressive disorders, and TNF-α is increased in chronic central nervous system (CNS) diseases, such as Alzheimer’s disease and multiple sclerosis." (PMID 34205595, 2021). "TNF antagonism seems to be particularly effective in patients with treatment-resistant depression, signs of inflammation (CRP > 5 mg/L) and elevated plasma lipids and cholesterols." (PMID 33653423, 2021). "The inflammatory etiology of fatigue and depression in MS was supported by evidence of increased serum and CSF concentration of inflammatory mediators such as TNF, interleukins (IL-1a, IL-1b, IL-6), IFNγ, and neopterin." (PMID 35242093, 2021). "Interleukins such as IL-1β, IL-6, and TNF-α become elevated in the brain during chronic stress and depression." (PMID 34078872, 2021). "Depression has sustained a series of inflammatory state, and promoted the increase of inflammatory markers, such as tumor necrosis factor-α (TNF-α), C-reactive protein (CRP) and interleukin 6 (IL-6)." (PMID 34421539, 2021). "Although TNF-α tends to decrease after medication treatment in pediatric depression, an increase in TNF-α level was observed after treatment in adult depression." (PMID 34576215, 2021). "In people suffering from depression, increased levels of interleukins: IL-6 and IL-1, as well as TNFα (tumor necrosis factor α) and interferon γ have been found." (PMID 33809367, 2021).
depression (continued). "A meta-analysis based on 29 studies of serum cytokines indicated increased sIL-2R, IL-6, and TNF-α levels, supporting the notion that elevated cytokine proinflammatory levels contribute to the pathophysiology of depression." (PMID 34200240, 2021). "TNF-α levels were increased in cases of pediatric and adult depression, but the response to treatment differed." (PMID 34576215, 2021). "Recently, we reported that the pharmacological manipulation of cellular stress pathways can induce depression phenotype in rats, which involved TNF-α, NF-κB, and TLRs73." (PMID 33483466, 2021). "The ‘coded’ effect associated with proinflammation activates and maintains a cascade of biological (IL-6, IL-17, TNF, TRYCATs) and psychological (anxiety) events acting on a feedback principle and contributing to drug resistance in depression." (PMID 33385173, 2021). "In particular, an increase in proinflammatory cytokines like IL-6 and TNF-α and a decrease in the neurotrophin BDNF are often associated with anxiety and depression in patients as well as experimental models." (PMID 34638592, 2021). "An experimental study showed that XPJYD reduced the serum and hippocampal levels of IL-6, TNFα, and other inflammatory factors in depression model rats and improved their learning and memory behaviors." (PMID 34257681, 2021). "Because of the significant association between ratio TNF-α/BDNF and depression severity together with the significant decrease in depression severity during the ECT-course in our cohort, one would expect a decrease in the ratio TNF-α/BDNF as well." (PMID 34841285, 2021). "A recent metanalysis characterized an inflammation profile in depression with elevated IL-6, tumor necrosis factor (TNF)-alpha, other cytokines, and chemokines." (PMID 33801190, 2021). "Treatment strategies currently trialled for patients with depression presenting with increased inflammation include the use of anti-inflammatory medications, such as minocycline and tumor necrosis factor (TNF)-alpha inhibitors." (PMID 34192271, 2021). "Anti-cytokine pharmacotherapies including TNF- α blockers (etanercept and infliximab) have been shown to attenuate depressive mood and inhibit cognitive decline in BD and Major Depressive Disorder (MDD)." (PMID 34112182, 2021). "There is now ample evidence that the levels of pro-inflammatory cytokines (IL-1β, IL-6, or TNF-α) are elevated in depressed patients and animal models of depression." (PMID 35011254, 2021). "Si-Ni-San reduces the release of inflammatory factors IL-1β, IL-6, IL-2, and TNF-α in the peripheral fluid of patients with post-stroke depression and regulates the over-activation of the HPA axis, thereby exerting an antidepressant effect." (PMID 33790789, 2021). "Conversely, anti-TNF significantly improved depressive symptoms (Hospital Anxiety and Depression Rating Scale HADS) at both 24-h (P = 0.015) and 12 weeks (p = 0.018)." (PMID 32457424, 2021). "So far, only a few studies have investigated immune markers in adolescents with depression, mainly focusing on levels of inflammatory proteins and suggesting a possible increase in TNF." (PMID 34927102, 2021). "Recent evidence from both clinical and preclinical research studies indicates that elevations in pro-inflammatory cytokines, including IL-6, TNF-α, and NO, act as a common mechanism for the impact relationship of depression and fatigue in patients with CRF." (PMID 34122094, 2021). "The expression of TNF-α in the dorsolateral prefrontal cortex of patients with severe depression is significantly increased." (PMID 34479552, 2021). "Proinflammatory cytokines such as interleukin (IL)-1β, IL-8, and tumor necrosis factor-α (TNF-α) among patients with depression have been reported to be significantly upregulated." (PMID 35155523, 2021). "The IL-1β, IL-6, and TNF-α proinflammatory cytokines were previously reported as elevated in patients with depression and appear to play significant roles in the pathogenesis of major depression." (PMID 34209804, 2021).
depression (continued). "Pro-inflammatory cytokines, including IL-1β, IL-6, IL-12, TNF-α, and IFN-γ, are thought to be associated with depressive disorders." (PMID 34576215, 2021). "Tumor necrosis factor-α (TNF-α) mean (SD) pg/ml serum concentrations by TNF-α two polymorphisms and depressive disorder status at 2 weeks and at 1 year after acute coronary syndrome (ACS)." (PMID 34630187, 2021). "Evidence suggests that some inflammatory mediators, such as tumor necrosis factor alpha (TNF-α) and interleukin-1beta (IL-1β), are involved in the development of depressive disorders." (PMID 33564342, 2021). "At the end of therapy, comparison of TNF groups revealed significantly lower depression-scores in hTNF compared to lTNF patients (5.47 compared to 7.92, p = 0.035, d = 0.504)." (PMID 33240126, 2020). "The main general markers of the cooccurrence of chronic pain and depression were related to central inflammation, particularly, tumor necrosis factor (TNF)-α, interleukin (IL)-1β, and IL-6, as well as peripheral discrepancies in cortisol levels." (PMID 32849076, 2020). "Interleukin-6 (IL-6) and tumor necrosis factor-α (TNF-α) levels were significantly increased in patients with depression." (PMID 33447180, 2020). "Emerging evidence indicates that proinflammatory cytokines, including interleukin (IL)-1, IL-6, and tumor necrosis factor-alpha (TNF-α), contribute to the pathophysiology of depression." (PMID 33029297, 2020). "The 24-item Hamilton Depression Scale (HAMD-24) score was positively correlated with the level of TNF-α in CSF." (PMID 33192466, 2020). "As a primary outcome, mPT success, evidenced by delta HADS “depression,” was analyzed according to tumor necrosis factor alpha (TNFα) production by peripheral blood mononuclear cells (PBMC) after phytohemagglutinin (PHA) challenge at baseline." (PMID 33240126, 2020). "Stress is associated with higher levels of proinflammatory cytokines, such as tumor necrosis factor-α (TNF-α) and interleukin (IL)-6, in patients with depression compared with healthy individuals." (PMID 33343332, 2020). "Compared with these two groups, higher levels of SOD, CAT, and GSH-Px but lower levels of CRP, IL-6 and TNF-α were observed in the depression group." (PMID 32973539, 2020). "This regression model was only calculated for the PG group, as this group presented a pro-inflammatory marker (i.e. TNF-α) that correlated with both depression and two fatigue dimensions (COG-F and PSY-F)." (PMID 32528052, 2020). "We aimed to investigate the relationship between gray-matter (GM) structural networks and serum TNF-α in patients with major depression disorder (MDD) using multivariate source-based morphometry (SBM)." (PMID 32522975, 2020). "A meta-analysis of 24 studies reported that interleukin-6 (IL-6) and tumor necrosis factor-α (TNF-α) were found in higher concentrations in individuals with depression, compared with control participants." (PMID 33424964, 2020). "Among patients starting biologic therapy with tumor necrosis factor-α inhibitors (anti-TNF) the proportion with comorbid depression is 19%." (PMID 32072134, 2020). "Among inflammatory markers, IL-6, C-reactive protein (CRP), TNF-α and soluble interleukin-2 receptor (sIL-2R) appear to have the greatest potential to serve as markers for depression." (PMID 33255237, 2020). "A previous epidemiological prospective cohort study noted that Jia-Wei-Xio-Yao-San ameliorated depression in menopausal women compared with those administered antidepressants by increasing the serum TNF-α after 12 weeks of treatment." (PMID 33381200, 2020). "A study found that, in treatment-resistant patients with major depression, administration of the TNF-α antagonist, infliximab, alleviated depressive symptoms in subjects with elevated basal inflammatory markers." (PMID 32545890, 2020).
depression (continued). "The TNF antagonist infliximab has been shown to markedly reduce inflammatory marker concentrations and symptoms of depression, including motivational deficits, in people with major depression with increased inflammation (> 5 mg/L)." (PMID 32153436, 2020). "The current meta-analysis data show that compared with normal individuals, the levels of various inflammatory mediators (including tumor necrosis factor (TNF)-α, IL-6, and IL-1 receptor antagonists) in depression patients are increased." (PMID 32549286, 2020). "There was also a positive correlation between TNF-α levels and depressive symptoms (assessed with the Beck depression inventory) that both decreased with curcumin administration." (PMID 33329109, 2020). "We report a significant response to multimodal psychotherapeutic inpatient therapy (mPT) following a psychodynamic concept in patients with moderate depression and high production of TNFα by PBMC at the time of hospital admission." (PMID 33240126, 2020). "STAT3 is one of the transcription factors regulating the production of the cytokine IL-6, IL-10, TNF-α, and IL-1β, which have been shown to be involved in depression." (PMID 32655424, 2020). "Based on the univariate analysis of the GLM, we found significant differences in the years of education, cytokines (IL-1β, IL-2, IL-6, IL-12p70, IL-17A, IFNγ, TNFα, IL-10, and IL-13), and depression severity (indicated by the PHQ) among the groups." (PMID 32703187, 2020). "Tumor Necrosis Factor-α is another inflammatory cytokine, constantly and repeatedly reported to be increased in depression as compared to healthy controls; however certain meta-analyses found this to be inconclusive." (PMID 33255237, 2020). "In the cerebrospinal fluid (CSF) isolated from depression patients, upregulated expression of proinflammatory cytokines produced by M1 macrophages such as TNFα, among others, have been extensively reported." (PMID 32380663, 2020). "What's more, it was a well‐known fact that there was a relationship between depression and the increased TNF‐α plasma level." (PMID 32307924, 2020). "It has been reported that patients with depression are prone to have higher status of proinflammatory cytokines, including interleukin (IL)-1β, IL-6 and tumor necrosis factor α (TNFα) in the periphery and central nervous system." (PMID 31915015, 2020). "A meta-analysis of 82 studies provided evidence that peripheral levels of several pro-inflammatory cytokines (i.e. interleukin-6 and TNF-α) were more elevated in patients with major depression disorder compared to healthy controls." (PMID 32072134, 2020). "Peripheral blood of patients with major depression was shown to have a significant increase in inflammatory cytokines, such as tumor necrosis factor (TNF)-alpha, interleukin (IL)-1, IL-6 and other acute phase proteins related to inflammation." (PMID 33076303, 2020). "Decreased levels of antioxidant coenzyme Q (CoQ) which induce impaired antioxidant protection and enhanced production of damaging TNF-α have been reported in depression." (PMID 33255237, 2020). "In this study, we investigated the effects of acupuncture on blood and brain regional tumor necrosis factor alpha (TNF-α) in rats with depression and chronic somatic pain comorbidity." (PMID 33144854, 2020). "Litratures indicate that the patients with depression usually possess high concentrations of pro-inflammatory cytokines (for instance; IL-6, and TNF-α) as compared with normal individuals." (PMID 33415126, 2020). "Peripheral injection of R-BHB was also able to decrease IL-1β and TNF-α levels in the hippocampus of rats in this depression model." (PMID 33014275, 2020). "Proinflammatory cytokines, including IL-1β, IL-6, and TNF-α, are elevated in experimental and clinical studies of depression." (PMID 32410849, 2020).
depression (continued). "Meta-analyses have shown that inflammation is connected with depression, i.e., the elevated C-reactive protein, interleukin 6 (IL-6), and tumor necrosis factor alpha (TNF-α) in major depressive disorder." (PMID 32581890, 2020). "PD patients have elevated levels of CRP, CCL-2, IL-6, and of TNF-alpha, correlating partially with fatigue, depression and anxiety, and with cognitive deficits." (PMID 32072462, 2020). "Several clinical studies have consistently reported that the serum TNF-α levels are increased in patients with depression." (PMID 33364982, 2020). "Peripheral levels of pro-inflammatory cytokines IL-6 and TNF-α are elevated in depression patients who were SSRI resistant compared to patients with depression, but in remission whose cytokine levels were similar to matched healthy controls." (PMID 32539844, 2020). "Postmortem analysis of the PFC of suicide victims has shown elevated levels of inflammatory cytokines such as IL‐1β, IL‐6, and TNF‐α 40, and suicide victims that have suffered from depression and schizophrenia exhibit increased microglial reactivity." (PMID 32125791, 2020). "Both EA and acupuncture can significantly decrease TNF-α and IL-6 expression, which provides antidepressant effects and improves the hippocampal neuroinflammation in animal models of depression." (PMID 33343332, 2020). "Elevated inflammatory cytokine, soluble interleukin 2 receptor (sIL-2R) and tumor necrosis factor-α, may be associated with depression and anxiety in PD, which also imply the underlying neuro-inflammatory process may contribute to the development of depression and anxiety in PD." (PMID 32716954, 2020). "Blocking proinflammatory cytokines such as TNF, has been shown to decrease depressive symptoms in patients with major depressive disorder." (PMID 32380663, 2020). "These pathways are linked to the core genes chiefly including FOS, IL6, TNF-α, Bcl-2, c-Jun, ERK, and EGF gene in our research in the treatment of depression." (PMID 32997725, 2020). "Patients with major depressive disorders exhibit increased circulating pro‐inflammatory cytokines, particularly tumor necrosis factor alpha (TNF‐α; Anisman & Hayley, 2012; Lichtblau, Schmidt, Schumann, Kirkby, & Himmerich, 2013)." (PMID 31945269, 2020). "TNF-α is one of the most thoroughly studied pro-inflammatory biomarkers for both depression and T2DM." (PMID 32971941, 2020). "In this study, it was found that the higher the level of TNF-α in CSF, the severer the symptoms of depression in PD patients." (PMID 33192466, 2020). "Third, accumulating evidence indicates that depression is related to a state of chronic low-grade inflammation, with significantly increased levels of interleukin (IL)-1, IL-6, tumor-necrosis factor (TNF)-alpha and C-reactive protein (CRP)." (PMID 32228541, 2020). "TNF-α influences many chemical and immune regulatory pathways that are related to and characteristic of depression." (PMID 32321532, 2020). "Meta-analyses showed that patients with depression exhibit higher expression levels of pro-inflammatory cytokines, including interleukin-6 (IL-6) and the tumor necrosis factor-α (TNF-α), compared with healthy control subjects." (PMID 32518376, 2020). "There are growing evidences from clinical and preclinical studies implying that TNF‐α is potentially to play a crucial role in the pathogenesis of depression." (PMID 32307924, 2020). "In this sense, the main general markers of the cooccurrence of chronic pain and depression are related to central inflammation, particularly TNF-α, IL-1β, and IL-6." (PMID 32849076, 2020). "For example, inhibition of TNF was shown to improve symptoms in people with major depression, but only in those with heightened immune biomarkers." (PMID 33061891, 2020). "TNFα was shown in a meta-analysis to interfere with depression treatment success more frequently than other cytokines." (PMID 33240126, 2020).